TRPV2 (transient receptor potential cation channel subfamily V member 2)
Diseases named in the same sentence as TRPV2 in open-access papers (continued):
Sharing a sentence is not in itself a finding about the gene and the disease.
muscular dystrophy (11 papers, 2013 to 2025). Muscular dystrophy (MD) refers to a group of more than 30 genetic diseases characterized by progressive weakness and degeneration of the skeletal muscles that control movement. "In cardiomyocytes, the role of TRPV2 in pathophysiology was demonstrated—in cells from animals with muscular dystrophy, the overexpression of TRPV2 was shown, which led to an increase in the plasma concentration of Ca2+." (PMID 40724903, 2025). "In our previous pilot study, we showed that tranilast, a TRPV2 inhibitor, reduced brain natriuretic peptide levels in two patients with muscular dystrophy and advanced heart failure." (PMID 39789553, 2025). "Overexpression of TRPV2 at the sarcolemma was observed in the skeletal muscle and cardiomyocytes of patients with muscular dystrophy (MD) and animal models of MD such as mdx mice and BIO 14.6 hamsters." (PMID 36768491, 2023). "TRPV2 has also been found to be upregulated in various models of muscular dystrophy (MD), a multifaceted disease that is characterized by development of progressive muscle weakness and is commonly associated with development of dilated cardiomyopathy (DCM)." (PMID 34867442, 2021). "The critical role of TRPV2 in muscular dystrophy was demonstrated using a dominant-negative strategy." (PMID 29581825, 2018). "Notably, TRPV2 has been involved in some hereditary diseases, such as muscular dystrophy, being a player in the pathogenesis of myocyte degeneration, and cell stretch increases TRPV2 translocation to the sarcolemma leading to external Ca2+ overloading in animal models and patients." (PMID 25257900, 2014). "We reported that TRPV2 accumulated in the sarcolemma of heart muscle cells and skeletal muscles cells in patients with DCM and muscular dystrophy, respectively." (PMID 29581825, 2018).
endometrial cancer (10 papers, 2020 to 2025). Primary or metastatic malignant neoplasm involving the endometrium (mucous membrane that lines the endometrial cavity). "In contrast, the over-expression of TRP family members TRPV2 and TRPC1 in the same study of endometrial cancer cells was associated with the Epithelial–Mesenchymal Transition and more aggressive tumors." (PMID 40332161, 2025). "Another possible therapeutic target for endometrial cancer is the transient receptor potential cation channel subfamily V member 2 (TRPV2)." (PMID 39337406, 2024). "Consistently, CBD enhanced the cytotoxic effect of doxorubicin in an endometrial cancer cell line overexpressing TRPV2 to a greater extent than was observed in parental cells with regular TRPV2 expression." (PMID 36769206, 2023). "Of all the 27 human TRP channel genes examined, TRPV2 shows the highest expression in endometrial carcinoma, where elevated TRPV2 mRNA expression heralds an adverse outcome." (PMID 37240443, 2023). "In urothelial carcinoma and endometrial carcinoma, TRPV2 is highly expressed in cancer tissues, and the TRPV2 agonist cannabidiol activates apoptosis." (PMID 35406761, 2022). "As such, TRPV2 and TRPC1 are associated with the mesenchymal cell phenotype and are upregulated in both endometrial cancer biopsies and cancer cells with a higher EMT status." (PMID 34936030, 2021). "Overall, these results suggest that, like in tissue biopsies, the expression of TRPV2 and TRPC1 are associated with increased EMT status (or invasiveness), while TRPM4 expression is correlated with a low EMT status in endometrial cancer cells." (PMID 34936030, 2021). "Nevertheless, our results obtained in EC cells suggest that increased functional expression of TRPV2 in cancer cells might contribute, at least in part, to endometrial cancer progression." (PMID 34936030, 2021). "In addition, CBD enhanced the cytotoxic effect of paclitaxel in endometrial cancer cell lines regardless of TRPV2 overexpression." (PMID 36769206, 2023).
heart failure (10 papers, 2014 to 2025). Inability of the heart to pump blood at an adequate rate to meet tissue metabolic requirements. "Nevertheless, published evidence suggests that dilated cardiomyopathy, a severe disorder defined by ventricular dilation and contractile dysfunction, is associated with an accumulation of TRPV2 in cardiomyocytes in various heart failure animal models and in patients." (PMID 25136832, 2014). "The findings suggest that tranilast can inhibit TRPV2 expression for an extended period and is effective in preventing the worsening of cardiac function and subsequent death from heart failure." (PMID 39789553, 2025). "Tranilast is safe and effective in inhibiting TRPV2 expression, even in MD patients with advanced heart failure." (PMID 35578298, 2022). "Studies have found that inhibiting TRPV2 activity can effectively improve heart function in patients with heart failure." (PMID 33763489, 2021). "The activation of TRPV2 for patients with heart failure is ongoing and has recruited a handful of patients." (PMID 34867442, 2021). "Hsp20-S10F mice treated with probenecid had decreased mortality, hypertrophy, TRPV2 expression and molecular parameters of heart failure." (PMID 32218573, 2020). "Probenecid has been used for decades in the treatment of gout but recently has also been found to improve outcomes in patients with heart failure via stimulation of the transient receptor potential vanilloid 2 (TRPV2) channel in cardiomyocytes." (PMID 32218573, 2020). "While we already mentioned the effect of tranilast on sarcolemma TRPV2 in the cardiomyopathic hearts in Section 4.3, tranilast has long been reported to be effective in treating heart failure, for example also canine heart failure." (PMID 31394715, 2019). "Our data suggest that TRPV2 inhibitor therapy may be effective in patients with MD and advanced heart failure." (PMID 39789553, 2025). "Indeed, TRPV2 inhibition using mutant TRPV2 and Ca2+ handling agents was effective against heart failure and motor function in animal models of MD." (PMID 36768491, 2023). "These patients showed an improvement in echocardiographic findings after more than one year of tranilast administration, suggesting that inhibition of TRPV2 might become a new therapeutic target for heart failure and myopathy." (PMID 36768491, 2023). "Since the degranulation is caused by TRPV2 activation, it is thought that activation of TRPV2 in the mast cells within the cardiac muscles as well as cardiac muscles themselves would play an important role in the progression and/or deterioration of heart failure." (PMID 31394715, 2019). "Our previous pilot study showed that tranilast, a TRPV2 inhibitor, reduced brain natriuretic peptide (BNP) levels in two MD patients with advanced heart failure." (PMID 35578298, 2022). "In this clinical trial, TRPV2 expression on the mononuclear cell surface was reduced after administration of tranilast and cardiac biomarkers such as BNP remained stable, suggesting a protective effect of tranilast against the progression of heart failure." (PMID 36768491, 2023).
liver cancer (8 papers, 2020 to 2026). An epithelial or non-epithelial malignant neoplasm that arises from the liver. "In liver cancer, high expression of TRPV2 is association with poor prognosis in HCC patient." (PMID 40936093, 2025). "A contrasting role was described for TRPV2 overexpression in liver cancer in which its activity inhibited spheroid and colony formation and reduced stem cell markers expression in HepG2 cells." (PMID 34671260, 2021). "Another link was found between TRPV2 expression and either drug-induced cytotoxicity or stemness of liver cancer." (PMID 33376561, 2020). "Additional studies have demonstrated a link between TRPV2 expression and either drug-induced cytotoxicity or the stemness of liver cancer." (PMID 33376561, 2020). "It has also been suggested that TRPV2 is a possible target for the therapeutic destruction of liver cancer stem cells." (PMID 32987945, 2020). "Some studies consider TRPV2 as a potential target for the treatment of human liver cancer patients." (PMID 38397045, 2024). "TRPV2 in the liver is currently known to mediate the survival of liver cancer cells." (PMID 38397045, 2024). "Indeed, blocking TRPV2 with tranilast, increased in vitro spheroid and colony formation and stem cell marker expression in liver cancer cell lines." (PMID 34671260, 2021). "Additionally, the expression of TRPV2 protein was linked to the stemness of liver cancer cells, as the knockdown of TRPV2 in HepG2 cells induced the expression of liver cancer stem-like cells (LCSLCs) markers." (PMID 32182937, 2020). "Measurement of the expression of TRPV2 together with liver cancer stem cell marker proteins in several liver cell lines and in HCC liver samples has provided some evidence that increased expression of TRPV2 in HCC cells reduces their ability to act as liver cancer stem cells." (PMID 32987945, 2020). "Interestingly, in the liver cancer cell line HepG2, shRNA-based TRPV2 knockdown promoted the expression of stem cell markers (i.e., CD133, CD44, and ALDH1), spheroid, and colony formation." (PMID 33376561, 2020). "Additionally, TRPV2 overexpression has been found in moderate and well differentiated liver cancer compared to poorly differentiated liver cancer; as expected, channel activation inhibits tumor growth in vivo and mediates H2O2-induced oxidative stress and cell death in liver cancer cell lines." (PMID 41562849, 2026). "Similarly, the TRPV2 antagonist tranilast induced expression of liver cancer stem-like cell (LCSLC) markers and led to spheroid and colony formation, whereas the TRPV2 agonist probenecid produced an opposite effect on liver cancer cell lines." (PMID 33376561, 2020).
melanoma (8 papers, 2019 to 2025). A malignant, usually aggressive tumor composed of atypical, neoplastic melanocytes. "Using gain‐ and loss‐of‐function approaches, we established that TRPV2 expression and activity potentiates the acquisition of both the migratory and invasive phenotypes of melanoma cells, while dispensable for their proliferative/survival behaviors." (PMID 36744297, 2023). "By analyzing TRPV2 protein expression in an extended panel of melanoma cell lines harboring either mutation, we consistently detected high amounts of TRPV2 regardless of the mutational status." (PMID 36744297, 2023). "Interestingly, in advanced melanoma models, TRPV2 also associates with the intermediate filament vimentin network, conceivably in order to extensively regulate cytoskeletal organization and adhesion structures mechanical maturation." (PMID 36744297, 2023). "Most importantly, survival analysis evidenced that melanoma tumors expressing high levels of TRPV2 correlated with shorter life expectancies in patients, compared to low TRPV2 expressers." (PMID 36744297, 2023). "Surface protein biotinylation experiments evidenced that the subset of TRPV2 channels present at the PM increased gradually with the invasive potential of the tested melanoma cell line." (PMID 36744297, 2023). "Using combined immunohistochemical and tissue microarray (TMA) analyses, we assessed TRPV2 expression in situ over 100 patient samples, including 62 malignant melanomas (Grade I‐IV), 20 lymph node metastases and 18 benign nevi." (PMID 36744297, 2023). "TRPV2 requirement for the formation of melanoma metastasis was likewise validated in the experimental model of xenografted zebrafish allowing a direct comparison of the metastatic potential of two different cell lines in the same organism." (PMID 36744297, 2023). "The mechanosensitive TRPV2 channel positively regulates the invasive potential and metastatic dissemination of melanoma cells, providing a new biomarker and potential migrastatic target for cutaneous metastatic melanoma." (PMID 36744297, 2023). "By querying transcriptomic data from the NCI‐60 panel and the Broad‐Novartis cancer cell line encyclopedia (CCLE), we evidenced that the exacerbated expression of TRPV2 was distinctive from melanoma cell lines, as compared to other cancer‐derived cell lines." (PMID 36744297, 2023). "Regarding talin proteolysis, which largely depends upon extracellular Ca2+ signaling in our melanoma models, it exactly mirrored the fluctuations of calpain activity resulting from TRPV2 modulation." (PMID 36744297, 2023). "Altogether, these in vivo results established that melanoma tumor cells rely at least in part on TRPV2 to succeed in disseminating and form distant metastases." (PMID 36744297, 2023). "Here, we established that in melanoma tumor cells the expression of functional TRPV2 channels was correlated with invasiveness, making TRPV2 mandatory for the dissemination and formation of distant metastases in vivo." (PMID 36744297, 2023). "Despite overall steady melanoma cells areas, TRPV2 overexpression in 501mel cells was by itself sufficient to considerably promote F‐actin accumulation, whereas TRPV2 silencing in aggressive melanoma cells disrupted F‐actin network." (PMID 36744297, 2023). "Corroborating our 2D‐data, TRPV2 repression drastically precluded the 3D‐invasion capacity of metastatic melanoma cells." (PMID 36744297, 2023). "In vitro as well as in vivo, TRPV2 activity is sufficient to confer both migratory and invasive potentials, while conversely TRPV2 silencing in highly metastatic melanoma cells prevents aggressive behavior." (PMID 36744297, 2023). "In the broader CCLE melanoma cell lines dataset, the overall expressions of TRPV2 and POU3F2(BRN2) were also correlated." (PMID 36744297, 2023).
melanoma (continued). "In migrating metastatic melanoma cells, TRPV2 mediates at least part of the Ca2+ signal activating calpain‐mediated proteolysis of talin, hindering the mechanical maturation of adhesions while favoring their turnover." (PMID 36744297, 2023). "When assessed by confocal immunofluorescence, TRPV2 was consistently detected at the PM of the highly metastatic melanoma cell lines, WM266.4 and 451Lu." (PMID 36744297, 2023). "We hereby reported a central role for the prominently expressed Ca2+‐conducting TRPV2 channel during the dynamic process of melanoma cells metastatic dissemination and identified calpains as one of TRPV2 key functional targets in that context." (PMID 36744297, 2023). "TRPV2 expression has been evaluated in epidermal melanocytes, two human malignant melanoma, and two metastatic melanoma cell lines." (PMID 37892239, 2023). "At the assay end point, in vivo BLI showed that TRPV2‐silenced melanoma cells have lost their metastatic potential in mice, as compared to TRPV2‐expressing control cells." (PMID 36744297, 2023). "Consistent with previous observations on NHEM versus melanoma cell lines, TRPV2 mRNA level was found significantly higher in melanoma tumors, including primary and metastatic lesions, as compared to healthy or nevi samples." (PMID 36744297, 2023). "In invasive melanoma cells, TRPV2 channel localizes at the leading edge, in dynamic nascent adhesions, and regulates calcium‐mediated activation of calpain and the ensuing cleavage of the adhesive protein talin, along with F‐actin organization." (PMID 36744297, 2023). "In unstimulated melanoma cells, we evidenced that TRPV2 is localized at the PM and is active, yet we excluded a growth factor‐dependent regulation of its trafficking (unpublished observations)." (PMID 36744297, 2023). "As TRPV2 directly correlates to the aggressiveness of the tumor and to patient mortality in human melanoma biopsies, it stands out as a valuable biomarker for malignant tumors with bad prognosis." (PMID 36744297, 2023). "Here, we uncover the prominent expression of the plasma membrane TRPV2 calcium channel as a distinctive feature of melanoma tumors, directly related to melanoma metastatic dissemination." (PMID 36744297, 2023). "Altogether suggesting a link between the expression of functional TRPV2 channels and the BRN2‐associated invasive phenotype of melanoma cell lines." (PMID 36744297, 2023). "More specifically, within the TRP family, TRPV2 displayed the highest differential expression between human nevi and melanoma samples." (PMID 36744297, 2023). "Here, we showed that TRPV2 physically interacts with cofilin‐1 in metastatic melanoma cell lines (Fig EV3C)." (PMID 36744297, 2023). "Reciprocally, upon TRPV2 silencing in the metastatic melanoma cell lines (WM266.4 and 451Lu), both serum‐induced migration and, to a greater extent, invasion (through a matrigel layer) were strongly hampered (by 40–80% and 65–95%, respectively)." (PMID 36744297, 2023). "In human melanoma tissues, TRPV2 overexpression correlates with advanced malignancy and poor prognosis, evoking a biomarker potential." (PMID 36744297, 2023). "TRPM2, TRPM8, TRPV1, and TRPV2 have been identified in melanoma cell lines, where their expression and function confer susceptibility to apoptosis and necrosis." (PMID 34831352, 2021). "Overall, our studies revealed that TRPV4 and TRPV2 mediated melanoma cell death via channel activation and characterized the mechanism of functional TRPV4 ion channel in regulating AKT pathway driven antitumor process." (PMID 30881453, 2019). "Our data further indicated that activation of thermo-TRPV2/4 modulated distinct cellular behaviors in human melanoma cells." (PMID 30881453, 2019). "Our data showed that there was discordance between protein and gene expression, such as TRPV2 in human melanoma cells." (PMID 30881453, 2019).